ZNF92 (zinc finger protein 92)
Description:
May be involved in transcriptional regulation.
Synonyms: HPF12; TF12; HEL-203; HTF12
Tractability: PROTAC: ubiquitination databases record sites on it.
Gene: Protein-coding gene on chromosome 7 (65,373,799 to 65,401,136, forward strand). Ensembl gene ENSG00000146757.
Subcellular location: Nucleus
Subcellular location (Human Protein Atlas): Nucleoplasm
Pathways (Reactome):
Gene expression (Transcription): Generic Transcription Pathway
Gene Ontology:
Molecular function: protein binding; DNA-binding transcription factor activity; DNA-binding transcription factor activity, RNA polymerase II-specific; RNA polymerase II cis-regulatory region sequence-specific DNA binding; zinc ion binding
Biological process: regulation of DNA-templated transcription; negative regulation of transcription by RNA polymerase II
Cellular component: nucleus
Genetic constraint (gnomAD): Loss-of-function variants: 12 observed, 12.16 expected, observed/expected ratio (o/e) 0.99, 90% interval 0.63 to 1.58. The upper end of that interval is the gene's LOEUF score, 1.58, which puts it in group 6 of 6, group 1 being the genes least tolerant of losing a copy. Missense variants: 622 observed, 691.12 expected, observed/expected ratio (o/e) 0.9, 90% interval 0.84 to 0.96. Synonymous variants: 206 observed, 230.7 expected, observed/expected ratio (o/e) 0.89, 90% interval 0.8 to 1.
Homologues: Orthologues: chimpanzee ZNF730 (62% identical). Paralogues in human: ZNF737 (68% identical), ZNF98 (68% identical), ZNF430 (68% identical), ZNF431 (67% identical), ZNF257 (67% identical), ZNF66 (67% identical), ZNF723 (67% identical), ZNF680 (66% identical), ZNF675 (65% identical), ZNF273 (64% identical), ZNF626 (63% identical), ZNF730 (62% identical), and 6 more.
Diseases named in the same sentence as ZNF92 in open-access papers:
ZNF92 is named in the same sentence as 8 diseases in open-access papers, as found by Europe PMC text mining. Sharing a sentence is not in itself a finding about the gene and the disease. The quoted sentences say what the papers report.
breast carcinoma (4 papers, 2022 to 2025). "A number of these, such as CEBPB, ZNF117 and ZNF92, have been previously proposed as breast cancer markers and ZNF273 and ZNF727 have been reported as breast cancer hub genes." (PMID 38561804, 2024). "Consistent with this cell-origin pattern, we observed that some human breast cancers are strongly ZNF92 protein positive, and others are almost entirely ZNF92 negative." (PMID 36038558, 2022). "Remarkably, ZNF92 is distinctively over-expressed in breast cancer compared to other tumor types, on a par with the breast cancer specificity of the estrogen receptor." (PMID 36038558, 2022). "All the breast cancer cell lines we tested indicate that ZNF92 protein is co-expressed with HDAC7 in the nucleus." (PMID 36038558, 2022). "However, this region only includes one protein-coding gene, ZNF92 (603974), which is an unexplored transcription factor with higher expression in human T lymphocytes and breast cancer." (PMID 40403082, 2025). "Importantly, ZNF92 over-expression appears as specific for breast cancer as estrogen receptor (ER) and HER2." (PMID 36038558, 2022). "Therefore, discovering the striking breast cancer specific over-expression of ZNF92 is rather unexpected." (PMID 36038558, 2022). "In addition, we identified ZNF92, a transcription factor that has never been studied in cancer, as a marker that is almost uniquely over-expressed in human breast cancer." (PMID 36038558, 2022).
epilepsy (2 papers, 2013 to 2025). A brain disorder characterized by episodes of abnormally increased neuronal discharge resulting in transient episodes of sensory or motor neurological dysfunction, or psychic dysfunction. "Case 18 highlights ZNF92, a transcription factor expressed in prenatal brain and astrocytes, as a potential contributor to epilepsy and facial dysmorphology." (PMID 40869915, 2025). "The region 7q11, containing genes INTS4L1 and ZNF92, is a candidate locus for epilepsy." (PMID 23460800, 2013).
embryonal carcinoma (1 paper, 2022). A non-seminomatous malignant germ cell tumor characterized by the presence of large germ cells with abundant cytoplasm resembling epithelial cells, geographic necrosis, high mitotic activity, and pseudoglandular and pseudopapillary structures formation. "ZNFs are a large family of transcription factors that include ZNF92, which was identified in a screen of a human undifferentiated embryonal carcinoma cell line using the KRAB domain of ZNF8546." (PMID 36038558, 2022).
cancer (4 papers, 2016 to 2023). A tumor composed of atypical neoplastic, often pleomorphic cells that invade other tissues. "We utilized the Gene Set Cancer Analysis (GSCA) online platform to discover that ZNF92 expression is uniquely associated with sensitivity to the 90-kDa heat shock protein (Hsp90) inhibitor Tanespimycin (17-AAG), a synthetic analog of the antibiotic Geldanamycin." (PMID 36672285, 2023). "Previous to our study, ZNF92 had not been examined in any cancer type." (PMID 36672285, 2023).
ZNF92 also shares sentences with these, for which no sentence is quoted: tumor (4 papers); prostate carcinoma (3); bipolar disorder (1); breast tumors (1).